SNORA38 (small nucleolar RNA, H/ACA box 38)
Synonyms: ACA38
Gene: Small nucleolar RNA gene on chromosome 6 (31,623,079 to 31,623,210, forward strand). Ensembl gene ENSG00000200816.
Gene Ontology:
Biological process: RNA processing
Cellular component: Cajal body; nucleolus
Homologues: Orthologues: chimpanzee SNORA38 (100% identical), macaque SNORA38 (94% identical), pig SNORA38 (84% identical), mouse Gm23442 (82% identical), rat Snora38 (82% identical), guinea pig SNORA38 (80% identical). Paralogues in human: SNORA38B (83% identical).
Diseases named in the same sentence as SNORA38 in open-access papers:
SNORA38 is named in the same sentence as 5 diseases in open-access papers, as found by Europe PMC text mining. Sharing a sentence is not in itself a finding about the gene and the disease. The quoted sentences say what the papers report.
breast carcinoma (3 papers, 2022 to 2025). "snorA38 and snoRA71 were identified as part of a 20 snoRNA/scaRNA signature associated with breast cancer brain metastases." (PMID 41510246, 2025). "The present study identified the underlying mechanisms by which SNORA38 might influence the occurrence and development of breast cancer." (PMID 36158687, 2022). "snoRA38 is upregulated in breast cancer, and its expression levels correlated with tumor size, lymph node metastasis, and TNM stage." (PMID 41510246, 2025). "In conclusion, SNORA38 was significantly up-regulated in breast cancer tissues compared with normal tissues." (PMID 36158687, 2022). "In the public database and patients’ biopsies, SNORA38 was significantly up-regulated in breast cancer." (PMID 36158687, 2022). "snoRNA chips (Oebiotech, Shanghai, China) included 248 snoRNAs that were employed to investigate the differential snoRNAs expression between BCCs (breast cancer cells) and BCSCs, which revealed that SNORA38 was significantly overexpressed in CD44+CD24− subgroup." (PMID 36158687, 2022). "Meanwhile, SNORA38 was positively associated with the stem cell marker OCT-4, which suggested that SNORA38 might be related to breast cancer stemness." (PMID 36158687, 2022). "Second, breast cancer patients with high expression of SNORA38 had a poor prognosis that might be a prerequisite for SNORA38 to become a therapeutic target." (PMID 36158687, 2022). "According to TCGA analyses and experimental evidence, SNORA38 was highly expressed in breast cancer tissues and BCSCs, suggesting that overexpression of SNORA38 may promote malignant transformation and play an essential role in the genesis and development of breast cancer." (PMID 36158687, 2022). "First, the expression of SNORA38 in breast cancer tissues was higher than that in normal tissues, which was significantly correlated with tumor size, lymph node metastasis, and TNM stage, suggesting that SNORA38 may be related to the occurrence and development of breast cancer." (PMID 36158687, 2022).
colon cancer (1 paper, 2025). "Increased expression of snoRA38 and snoRA75 was observed in colon cancer metastasis to the liver." (PMID 41510246, 2025).
metastatic colorectal cancer (1 paper, 2025). "Other studies have confirmed strong correlations between Helicobacter cinaedi and Sphingobium herbicidovorans in metastatic colorectal cancer tissues with specific genes (such as SELENBP1 and SNORA38), providing new ideas for personalized treatment." (PMID 40852612, 2025).
cancer (4 papers, 2022 to 2025). A tumor composed of atypical neoplastic, often pleomorphic cells that invade other tissues. "SnoRNAs with elevated expression in GSC and GBM lines (snoRA38, snoRA51, snoRA71, and snoRA75) have been previously implicated in cancer development." (PMID 41510246, 2025). "Particularly, SNORA38 has been identified as an oncogene in certain cancer types, playing a role in cellular proliferation and survival." (PMID 38357363, 2023).
tumor (2 papers, 2022 to 2025). "Because the molecular function of SNORA38 has not been fully studied, further studies are needed to clarify its role in tumor genesis and metastasis." (PMID 36158687, 2022).